AKR1C1 (aldo-keto reductase family 1 member C1)
Description:
Cytosolic aldo-keto reductase that catalyzes NADPH-dependent reduction of ketosteroids to hydroxysteroids. Displays broad substrate specificity with distinct positional and stereochemistry, primarily generating 20alpha-hydroxysteroids, but also 3alpha/beta- and 17beta-hydroxysteroids. Involved in neurosteroid metabolism. Reduces 5alpha-dihydrodeoxycorticosterone (5-alpha-DHDOC) to neuroactive steroid 3alpha,5alpha-tetrahydrodeoxycorticosterone (3alpha,5alpha-THDOC) known to alter neural excitability via allosteric activation of gamma-aminobutyric acid type A (GABAAR) receptors. Inactivates 3alpha-hydroxy-5alpha-pregnan-20-one (3alpha,5alpha-THP) into less potent neurosteroid 3alpha,20alpha-dihydroxy-5alpha-pregnane. Catalyzes the reduction of progesterone to less potent progestogen (20S)-hydroxypregn-4-en-3-one likely regulating ligand availability for progesterone receptors. In androgen catabolism, may predominantly act as a phase I enzyme by introducing a hydroxyl group prior to conjugation. It can nevertheless participate in the alternative phase II pathway by directly reducing sulfate- or glucuronide-conjugated androgens. In vitro can efficiently catalyze bidirectional conversion between ketosteroids and hydroxysteroids using NADPH/NADP(+) or NADH/NAD(+) as cofactors. In vivo however, the reductase activity prevails since the major reducing cofactor NADPH inhibits NAD(+)-dependent oxidase activity.
Synonyms: 20-alpha-HSD; DD1; HBAB; DDH; DDH1; MBAB; HAKRC; 2-ALPHA-HSD; DD1/DD2; H-37
Tractability: Small molecule: a structure with a bound ligand is known; a high-quality ligand is known; it has a high-quality binding pocket; it belongs to a druggable protein family. PROTAC: ubiquitination databases record sites on it; its protein half-life has been measured; a small molecule that binds it is known.
Target class: Enzyme; Oxidoreductase
Gene: Protein-coding gene on chromosome 10 (4,963,253 to 4,983,283, forward strand). Ensembl gene ENSG00000187134.
Subcellular location: Cytoplasm, cytosol
Subcellular location (Human Protein Atlas): Cytosol; Endoplasmic reticulum
Pathways (Reactome):
Metabolism: Synthesis of bile acids and bile salts via 24-hydroxycholesterol; Synthesis of bile acids and bile salts via 27-hydroxycholesterol; Synthesis of bile acids and bile salts via 7alpha-hydroxycholesterol
Drug ADME: Prednisone ADME
Sensory Perception: Retinoid metabolism and transport
Gene Ontology:
Molecular function: 17-beta-hydroxysteroid dehydrogenase (NADP+) activity; 3-alpha-hydroxysteroid 3-dehydrogenase [NAD(P)+] activity; 3-beta-hydroxy-5-beta-steroid dehydrogenase (NADP+) activity; 3-beta-hydroxysteroid 3-dehydrogenase (NADP+) activity; 5-alpha-androstane-3-beta,17-beta-diol dehydrogenase (NADP+) activity; aldose reductase (NADPH) activity; androsterone dehydrogenase [NAD(P)+] activity; bile acid binding; carboxylic acid binding; estradiol 17-beta-dehydrogenase [NAD(P)+] activity; ketosteroid monooxygenase activity; oxidoreductase activity, acting on NAD(P)H, quinone or similar compound as acceptor; protein binding; testosterone dehydrogenase (NADP+) activity; trans-1,2-dihydrobenzene-1,2-diol dehydrogenase activity; alcohol dehydrogenase (NADP+) activity; steroid dehydrogenase activity, acting on the CH-OH group of donors, NAD or NADP as acceptor; 17-alpha,20-alpha-dihydroxypregn-4-en-3-one dehydrogenase [NAD(P)+] activity; 17-beta-hydroxysteroid dehydrogenase (NAD+) activity; alcohol dehydrogenase (NAD+) activity; androstan-3-alpha,17-beta-diol dehydrogenase (NAD+) activity; carbonyl reductase (NADPH) activity; indanol dehydrogenase activity; oxidoreductase activity
Biological process: bile acid metabolic process; cellular response to jasmonic acid stimulus; daunorubicin metabolic process; digestion; doxorubicin metabolic process; epithelial cell differentiation; positive regulation of reactive oxygen species metabolic process; progesterone metabolic process; retinal metabolic process; bile acid and bile salt transport; cholesterol homeostasis; intestinal cholesterol absorption; prostaglandin metabolic process; retinoid metabolic process; xenobiotic metabolic process; hormone metabolic process; monocarboxylic acid metabolic process; steroid metabolic process
Cellular component: cytosol; endoplasmic reticulum; extracellular exosome
Genetic constraint (gnomAD): Loss-of-function variants: 30 observed, 32.43 expected, observed/expected ratio (o/e) 0.93, 90% interval 0.69 to 1.25. The upper end of that interval is the gene's LOEUF score, 1.25, which puts it in group 5 of 6, group 1 being the genes least tolerant of losing a copy. Missense variants: 286 observed, 310.85 expected, observed/expected ratio (o/e) 0.92, 90% interval 0.83 to 1.01. Synonymous variants: 99 observed, 116.35 expected, observed/expected ratio (o/e) 0.85, 90% interval 0.72 to 1.01.
Homologues: Orthologues: macaque AKR1C2 (90% identical), zebrafish akr1a1a (42% identical), Drosophila melanogaster CG6083 (40% identical), Caenorhabditis elegans Y39G8B.1 (40% identical), zebrafish zgc:56622 (39% identical), Caenorhabditis elegans C07D8.6 (37% identical), Caenorhabditis elegans Y39G8B.2 (33% identical), zebrafish zgc:110366 (32% identical), Caenorhabditis elegans F53F1.2 (31% identical), Caenorhabditis elegans F53F1.3 (31% identical), tropical clawed frog XB5994047 (31% identical), Caenorhabditis elegans C01G5.5 (30% identical), and 9 more. Paralogues in human: AKR1C2 (98% identical), AKR1C3 (88% identical), AKR1C4 (83% identical), AKR1C8 (68% identical), AKR1D1 (58% identical), AKR1B1 (48% identical), AKR1B10 (48% identical), AKR1B15 (45% identical), AKR1A1 (43% identical), AKR1E2 (43% identical), AKR7A2 (26% identical), KCNAB3 (26% identical), and 4 more.
Diseases named in the same sentence as AKR1C1 in open-access papers:
AKR1C1 is named in the same sentence as 94 diseases in open-access papers, as found by Europe PMC text mining. Sharing a sentence is not in itself a finding about the gene and the disease. The quoted sentences say what the papers report.
breast carcinoma (25 papers, 2010 to 2025). "Several studies have linked AKR1C1 to different types of cancer, including breast cancer, gastric cancer, prostate cancer, and cervical cancer, and regulates tumor cell proliferation, metastasis, and chemotherapy-resistance in previous studies." (PMID 39478199, 2025). "In detail, patients with HER2+ breast cancer and high expression of AKR1C1 had a higher risk of recurrence than did patients with low AKR1C1 expression (Hazard Ratio [HR]=1.53, 95% Confidence Interval [CI] 1.01-2.32, p-value = 0.043)." (PMID 37469415, 2023). "Therefore, elevated levels of CD36, AQP7, LIPE, and AKR1C1 in mammary epithelial cells may serve as promising indicators for identifying high-risk breast cancer groups." (PMID 40868150, 2025). "Further, after the knockdown of AKR1C1 in human breast cancer cells HCC1806, we found that the apoptosis signaling pathway was significantly upregulated and the mean fluorescence intensity (MFI) of ROS was significantly increased." (PMID 39418072, 2024). "The overexpression of AKR1C1 was detected in both doxorubicin-resistant lung cancer cells and epirubicin-resistant breast cancer." (PMID 37173953, 2023). "Aberrant expression of AKR1C1 has been reported for ovarian cancer tissues and breast cancer cells, and studies have shown the crucial role of AKR1C1 in progesterone signaling." (PMID 35565391, 2022). "Using siRNA to silence Cul3 in breast cancer cells, microarray analysis revealed that the expressions of oxidative stress downstream genes (AKR1C1, UGDH, TXN, GCL, and NQO1) were overexpressed at least 2-fold." (PMID 35242279, 2022). "Comparing the human breast cancer cells MCF-7, T47-D, and MDA-MB-231 with the nontumorigenic breast epithelial MCF-10A cells, the expression of 5α-R and AKR1C1-3 isozymes were higher, and lower respectively in the breast cancer cell lines." (PMID 36614002, 2022). "We found that compared with TAM-sensitive breast cancer cells, the expression levels of AKR1C1, AKR1C2 and AKR1C3 genes were significantly increased in TAM-resistant breast cancer cells." (PMID 34886806, 2021). "In line, pyrithione-based ruthenium complexes have been successfully synthesised, demonstrating a potent inhibition of AKR1C1-3 and cytotoxic effects in breast cancer cells." (PMID 29515258, 2018). "Particularly in stromal fibroblasts and carcinoma cells, high AKR1C1 expression correlates with favorable tumor characteristics and longer survival in primary breast cancer patients." (PMID 27188717, 2016). "Five hundred nanometer TAM was used to treat breast cancer TMA-resistant cells that knocked out AKR1C1, AKR1C2 and AKR1C3 lines, its proliferation activity was significantly lower than the wild type, which directly indicated that high AKR1C1, AKR1C2 or AKR1C3 gene expression promoted TAM resistance." (PMID 34886806, 2021). "AKR1C1 and AKR1C2 were prognostic factors of breast cancer, and selective loss of these genes may help enhance endocrine therapy in breast cancer." (PMID 34778244, 2021). "Interestingly, AKR1C1 and AKR1C1-2 silencing in the T47-D breast cancer cell line enhanced the effect of P4 on decreasing cell numbers, which indicates that P4 metabolism could affect cellular death or proliferation processes in such cells." (PMID 36614002, 2022). "NRF2 knockdown had a pronounced effect on gene expression in MDA-MB-436 breast cancer cells, notably reducing multiple anti-ferroptosis genes, including SLC7A11, NQO1, TXNRD1, GCLM, and AKR1C1." (PMID 40867343, 2025). "CBM effectively prevented the inhibition of COX-1, COX-2, AKR1C1, and AKR1C2 while retaining AKR1C3 inhibition, making it a valuable molecular probe for studying AKR1C3’s role in breast cancer signaling and proliferation." (PMID 38523637, 2024). "In the context of breast cancer, which involves the use of anti-estrogen agents and aromatase inhibitors in hormone receptor-positive cases, AKR1C1, AKR1C2, and AKR1C3 have been found to be upregulated in tamoxifen-resistant breast cancer cells." (PMID 38523637, 2024).
breast carcinoma (continued). "A search of publicly available databases showed that the expression of the AKR1C1 and AKR1C2 genes is inversely correlated with the in vitro sensitivity to alpelisib in a large panel of breast cancer cell lines." (PMID 37469415, 2023). "Compared with TAM-sensitive counterparts, the expression levels of AKR1C1, AKR1C2, and AKR1C3 were up-regulated in TAM-resistant breast cancer cells." (PMID 34886806, 2021). "The results showed the AKR1C1, AKR1C2 and AKR1C3 were highly expressed in TAM-resistant breast cancer cells." (PMID 34886806, 2021). "The function of AKR1C1, AKR1C2 and AKR1C3 genes in TAM-resistant breast cancer cells was revealed by bioinformatics analysis and further confirmed by biological experiments." (PMID 34886806, 2021). "The protein expression levels of AKR1C1, AKR1C2 and AKR1C3 in TAM-sensitive and resistant breast cancer cells were compared." (PMID 34886806, 2021). "Analysis of The Cancer Genome Atlas (TCGA) showed that AKR1C1, AQP7, CD36, and LIPE display low genomic alteration frequency in breast cancer, and only CD36 expression has prognostic value (P = 0.005)." (PMID 33083529, 2020). "In a siRNA-mediated transient KEAP1 inhibition approach, AKR1C1, 1C2, 1C3, and other NRF2 target genes were increased in both human keratinocytes and breast cancer cell line." (PMID 23766854, 2013). "In breast cancer samples, the expression levels of AKR1C1-2 were lower when compared with the paired nontumoral tissue of the same patients." (PMID 36614002, 2022). "Here, the use of siRNA against CUL3 in MCF-7 breast cancer cells increased the levels of NRF2-regulated proteins, including GCL, NQO1, AKR1C1, UGDH, TXN and the drug transporter ABCC1, ultimately conferring a resistance to the oxidants and conventional anticancer agents." (PMID 33805996, 2021). "These tumors cluster with non-tumoral breast cancer cells and exhibit over-expression of PIK3R1 and AKR1C1, in addition to other genomic alterations." (PMID 20492711, 2010).
lung cancer (19 papers, 2014 to 2025). A malignant neoplasm involving the lung. "Mounting evidence reveals that AKR1C1 is volved in a variety of cancers, including hepatocellular carcinoma, lung cancer, gastric cancer, and cervical cancer, and the over-expression of AKR1C1 has been found to be associated with carcinogenesis." (PMID 34012402, 2021). "Overall survival analysis of lung cancer patients receiving pharmaceutical therapy revealed that the AKR1C1 high group presented a greater hazard ratio versus the AKR1C1 low group." (PMID 40687611, 2025). "STK11/KEAP1 co-mutations lead to a notable increase in the expression of ferroptosis-protective genes, including SCD and AKR1C1/2/3, as well as resistance to drug-induced ferroptosis in lung cancer cells." (PMID 37728413, 2023). "AKR1C1 acts as an important inducement in the proliferation and migration of lung cancer cells; the cytotoxicity of ALA was thus examined in human NSCLC cells." (PMID 35370661, 2022). "According to our analysis data of mRNA levels from the Oncomine Database and GEPIA, AKR1C1 in lung cancer samples had a significantly higher expression." (PMID 35370661, 2022). "An increasing body of evidence reveals that AKR1C1 shows a higher expression in a wide variety of cancers, including lung cancer, gastric cancer, and cervical cancer, than normal corresponding tissues." (PMID 35370661, 2022). "AKR1C1 displayed a higher expression level in cervical cancer, esophageal cancer, kidney cancer, lung cancer and lymphoma, especially in lung cancer." (PMID 34702254, 2021). "Cancer stem cells play a major role in drug resistance and tumor recurrence and AKR1C1/C2 are upregulated in a minor population of lung cancer stem cells." (PMID 31182137, 2019). "It is noteworthy that a recent publication on a lung cancer biomarker specific to the aldo-keto reductase (AKR) family of proteins states that one of these proteins identified in our NRMGS – AKR1C1 – can be used as a potential biomarker in lung cancer." (PMID 29050246, 2017). "Depression of plasma miR-182 and miR-185 in subjects exposed to high levels of PM2.5 and overexpression of SLC30A1, SERPINB2 and AKR1C1 in human lung cancer tissues were detected." (PMID 26338969, 2015). "The analysis of SLC30A1, SERPINB2 and AKR1C1 levels in human lung specimens from the TCGA database also revealed the aberrant expression of these genes in lung cancer tissues compared with paired normal tissues." (PMID 26338969, 2015). "We further analyzed SLC30A1, SERPINB2 and AKR1C1 mRNA expressions in human lung cancer retrieved from the TCGA database." (PMID 26338969, 2015). "Likewise, the cisplatin resistance of ovarian, cervical and lung cancers has been reported to be mediated by AKR1C1 and AKR1C2." (PMID 36139836, 2022). "Moreover, the relationship between AKR1C1 and the survival time of lung cancer patients after surgery was investigated." (PMID 35370661, 2022). "AKR1C1 promotes lung cancer progression in an enzyme-independent manner." (PMID 35883650, 2022). "Although these results did not provide direct evidence that the aberrant expression of SLC30A1, SERPINB2 and AKR1C1 in human lung cancer is caused by exposure to PM2.5, they did indicate a role in the development of lung cancer of these genes whose expression can be induced by PM2.5 organic extract." (PMID 26338969, 2015). "Increased expressions of SLC30A1, SERPINB2 and AKR1C1 were detected in human lung cancer." (PMID 26338969, 2015). "Our analysis also indicated that the three members of the aldo-keto-reductase-1C (AKR1C) family (AKR1C1, AKR1C2, AKR1C3) correlated with resistance to GPX4 inhibitors in lung cancer CLs." (PMID 39995872, 2025). "Similar protein-protein interaction between AKR1C1 and SIRT2 was also observed from another NSCLC NCI-H1299 cells, suggesting the formation of AKR1C1-SIRT2 complex in lung cancer models." (PMID 32104503, 2020).
lung cancer (continued). "Consistently, we found that YTHDF1 was decreased whereas AKR1C1 was increased by IHC in 100% (6/6) NSCLC patients resistant to platinum based neoadjuvant chemotherapy, whose lung cancer progression were examined by computerized tomography (CT) scan." (PMID 31653849, 2019). "AKR1C1 can activate STAT3, thereby promoting lung cancer metastasis." (PMID 33928101, 2021). "AKR1C1 is an aldosterone reductase with the function of catalyzing NAPDH-mediated reduction reaction, which is highly expressed in various cancers, such as liver cancer, lung cancer, and gastric cancer." (PMID 34938341, 2021). "More specifically, TIMP-2 was determined to decrease the SP in A549 lung cancer cells through decreased transcription of ABCB1 (ATP-binding cassette sub-family G member 1), ABCG2 (ATP-binding cassette sub-family G member 2), and AKR1C1 (Aldo-keto reductase family 1 member C1)." (PMID 26056585, 2014).
non-small cell lung carcinoma (18 papers, 2007 to 2025). A group of at least three distinct histological types of lung cancer, including non-small cell squamous cell carcinoma, adenocarcinoma, and large cell carcinoma. "Our previous studies have demonstrated that aldo-keto reductase 1C1 (AKR1C1) promotes non-small cell lung cancer (NSCLC) metastasis by directly interacting with signal transducer and activator of transcription-3 (STAT3) and reinforcing its activity." (PMID 40687611, 2025). "Another study demonstrated that YTHDF1 facilitates the hypoxic adaption of non-small-cell lung cancer via Keap1-nuclear respiratory factor 2 (Nrf2)-Aldo-keto reductase family 1 member C1 (AKR1C1) axis." (PMID 35804965, 2022). "AKR1C1 plays a key role in the regulation of autophagy and oxidative stress in the non-small cell lung cancer." (PMID 34249761, 2021). "Aldo-keto reductase family 1 member C1 (AKR1C1) promotes malignancy of Non-Small Cell Lung Cancer (NSCLC) by activating Signal Transducer and Activator of Transcription 3 (STAT3) pathway." (PMID 32104503, 2020). "Human breast and ovarian carcinoma have reduced expression while over expression of AKR1C1 was observed in patients with non-small cell lung cancer (NSCLC)." (PMID 24003325, 2013). "A previous study evaluated the relationship between the AKR1C and drug resistance and revealed that the over expression of AKR1C1/C2 led to drug resistance in non-small-cell lung cancer cells." (PMID 18034892, 2007). "In addition, their anticancer activities were screened using an Aldo–keto reductase (AKR)1C1 assay on A549 human non-small-cell lung cancer cells and the flower extract inhibited AKR1C1 activity." (PMID 36364218, 2022). "Moreover, AKR1B10 and AKR1C1 are overexpressed in non-small cell lung cancer and strongly correlate with Nrf2 activation." (PMID 35204145, 2022). "For example, overexpression of AKR1C1/2 was observed in non-small cell lung carcinoma." (PMID 28467356, 2017). "Additionally, the pro-inflammatory pathway was shown to increase AKR1C1/2 levels in non-small cell lung cancer cells leading to cisplatin and doxorubicin resistance." (PMID 26799320, 2016). "Moreover, the overexpression of AKR1C1/AKR1C2 may serve as a biomarker of chemoresistance in non-small cell lung cancer cells." (PMID 34778244, 2021). "Aldo-keto reductase family 1 member C1 (AKR1C1) is shown to be involved in the metastasis of cancer cells, particularly in non-small-cell lung cancer (NSCLC)." (PMID 40001571, 2025). "In non-small cell lung cancer (NSCLC) cell lines, AKR1C1 expression is upregulated." (PMID 39964621, 2025). "Acting as a specific inhibitor of AKR1C1, ALA selectively inhibits the activity of AKR1C1 and ALA treatment in human non-small-cell lung cancer (NSCLC) cell results in a reduction in cell proliferation and metastasis, inhibition of AKR1C1 expression, and deactivation of STAT3." (PMID 35370661, 2022).